BRAF (B-Raf proto-oncogene, serine/threonine kinase)
Diseases named in the same sentence as BRAF in open-access papers (continued):
Sharing a sentence is not in itself a finding about the gene and the disease.
melanoma (continued). "The sustained impact of melanoma cell protection against BRAF and MEK inhibition notably increased when freshly isolated neutrophils were added to the coculture at both time points, thus creating resistance by melanoma cells toward targeted therapy even for a longer period of at least 48 h." (PMID 38730718, 2024). "Using Roadmap data from primary melanocytes, and BRAF and NRAS mutant melanocytes, the authors noted that as melanocytes progressed towards melanoma, BRAF mutants exhibited a global decrease in the number of bivalent domains, while NRAS mutants had an increase." (PMID 38385532, 2024). "Trametinib, as a single agent, was approved in 2013 by the FDA for the treatment of metastatic BRAFV600E/K-mutant melanoma patients who have not been previously treated with BRAF inhibitors." (PMID 38731852, 2024). "The most common mutations in CSD and non-CSD melanomas affect BRAF, NRAS, and NF1 genes governing proliferation through action on the MAPK pathway, with BRAF and NRAS defined as oncogenes and NF1 as tumor suppressor gene." (PMID 38927967, 2024). "Common mutations in BRAF and neuroblastoma RAS viral oncogene homolog (NRAS), typically present in other melanomas, are absent in this context." (PMID 39202970, 2024). "BRAF and NRAS are two of the most common oncogenes involved in melanoma." (PMID 39336897, 2024). "Our results suggest that, although Panx1 deletion does not overturn the aggressive BRAF/Pten‐driven melanoma progression in vivo, it does increase the infiltration of effector immune T‐cell populations in the tumor microenvironment." (PMID 38327091, 2024). "We next wondered whether the additive and synergistic behaviors of BRAF and NRAS mutant melanomas observed in vitro occur at clinically relevant drug concentrations in patients." (PMID 39199684, 2024). "BRAF is a type of serine/threonine protein kinase that activates the MAP kinase/ERK signaling pathway, which acts as a driver gene in colon cancer, thyroid cancer, and melanoma." (PMID 39052013, 2024). "Immunostains were strongly positive for SOX10 and PRAME (preferentially expressed antigen of melanoma); while negative for BRAF, VE1, NRAS, Q61L, and DOG1." (PMID 38933829, 2024). "Indeed, our data suggest that oncogenic BRAF is able to control the levels of its natural inhibitor miR-579-3p through MITF regulation, thereby, preserving melanoma cells from the oncosuppressive functions of this microRNA." (PMID 38472212, 2024). "Altogether these data suggest that the impact of miR-579-3p on senescence programs are not dependent from MITF in BRAF-mutant melanoma cells." (PMID 38472212, 2024). "Currently, two BRAF-MEK inhibitor combinations, dabrafenib–trametinib and vemurafenib–cobimetinib, were FDA-approved on 9 January 2014 and 10 November 2015, respectively, for the treatment of unresectable or metastatic BRAF mutant melanoma." (PMID 38203795, 2024). "Here the authors report the results of a phase II trial of neoadjuvant cobimetinib (MEK inhibitor) and atezolizumab (anti-PD-L1) with or without the BRAF inhibitor vemurafenib in patients with resectable Stage III melanoma." (PMID 38365756, 2024). "NRAS, BRAF, and PTEN are some of the most significant genes in the development of melanoma." (PMID 38183141, 2024). "The most significantly enriched alterations in BRAF-mutant compared with non-BRAF-mutant melanomas were non-duplication SV events in CDKN2A (39/81, 48%; Fisher’s exact, OR = 2.41, 95% CI = 1.24–4.78, P = 7.8 × 10–3)." (PMID 38758740, 2024). "Since all the melanoma cell lines we used exhibited higher levels of p62 and DYRK3, this characteristic appears to be independent of the BRAF-V600E mutation." (PMID 38519031, 2024).
melanoma (continued). "While the concept of renewed responses upon rechallenge with BRAF/MEKi is known in melanoma, this does not explain all observed responses or stabilization of disease seen in this case series." (PMID 39682270, 2024). "However, the successful inhibition of this pathway using BRAF/MEK inhibitors has yielded clinically relevant benefits, leading to the establishment of these agents as standard treatment options for malignant melanoma and non-small cell lung cancer." (PMID 38333370, 2024). "BRAF and MEK inhibitors (BRAFi and MEKi) are now approved for the treatment of BRAFV600E/K melanoma and colorectal cancer; the MEKi, Selumetinib, is approved for the treatment of paediatric neurofibromatosis, a RASopathy driven by deregulated RAS activation and ERK1/2 inhibitors are in development." (PMID 38381045, 2024). "Virtually all patients with BRAF-mutant melanoma develop resistance to MAPK inhibitors largely through nonmutational events." (PMID 38300709, 2024). "When BRAF-MEK inhibition occurs, MITF suppression is relieved, allowing elevated levels of MITF to promote PGC1α-mediated mitochondrial biogenesis and OXPHOS in melanoma." (PMID 39501277, 2024). "However, in melanoma, TRIM28 upregulates the sensitivity of melanoma cells to targeted BRAF therapy by promoting the degradation of BCL2A1." (PMID 39100077, 2024). "In line with that, genetic alterations of both AMBRA1 and BRAF are prevalent in melanoma, while no AMBRA1 alterations have been identified in ATRT so far." (PMID 39617889, 2024). "Aneuploidy also does not correlate with melanoma PFS for BRAF-mutant melanoma patients receiving targeted therapy." (PMID 38473384, 2024). "High expression of genes related to the immune response was more frequent in melanomas of patients who achieved complete remission with BRAF and MEK inhibitors, while high expression of keratin and kallikrein genes was more frequent in melanomas of patients with rapid progression." (PMID 39272837, 2024). "The 14.5-month ongoing response discussed in this case is thus already at least as good, if not outperforming, the PFS estimates in BRAF-mutated NETs, as well as other solid organ tumors like ATC and melanoma." (PMID 38814411, 2024). "BRAF and mitogen-activated protein kinase kinase (MEK)-targeted therapies and immune checkpoint inhibitor (ICI) immunotherapy have led to remarkable improvements in response and survival outcomes in the advanced (unresectable stage III or IV melanoma) setting." (PMID 38907159, 2024). "The need of proximity was confirmed in experiments with conditioned medium showing a lack of protection for melanoma cells when exposed to dual BRAF/MEK inhibition compared to control cocultures." (PMID 38730718, 2024). "From a molecular point of view, miR-579-3p targets not only BRAF kinase, which is the main oncogenic driver of BRAF-mutant melanomas, but also the MDM2 oncoprotein, a well-known negative regulator of apoptosis." (PMID 38472212, 2024). "In a multi-institutional retrospective analysis of 229 melanoma patients, 60 patients (26%) had NRAS G12/G13/Q61 mutations, 53 patients (23%) had BRAFV600 mutations, and 116 (51%) had neither NRAS/BRAF mutations." (PMID 39195270, 2024). "Although so far, only BRAF is targetable, the establishment of NRAS and NF1 status is important as it will allow further research on the influence of these genes on the clinical behavior of melanoma." (PMID 39340537, 2024). "As a new result, we found that among the clinicopathological characteristics of the primary tumor, the Clark level of invasion and the localization of melanoma are significant and independent prognostic factors for both PFS and OS in metastatic patients treated with BRAF and MEK inhibitors." (PMID 39272837, 2024). "This relationship between BRAF class and age was independent of other clinical or genomic variables—such as RAS mutation status—in multivariable analyses and was observed in melanoma and other cancer types." (PMID 38275886, 2024).
melanoma (continued). "Specifically, a pre-clinical study in BRAFV600E melanoma demonstrated synergistic induction of apoptosis when BRAF or MEK inhibitors were combined with a MCL-1 inhibitor, which aligned with MCL-1 being the predominant pro-survival protein expressed in melanoma cells." (PMID 38429301, 2024). "Next, we applied the optimized pSILAC workflow to study how the immunopeptidomes of two melanoma cell lines with overactive MAPK pathway, Ma-Mel-63a (BRAF V600E) and UKE-Mel-105b (homozygous NRAS Q61R), are modulated by pharmacological inhibition of the MAPK pathway." (PMID 39835134, 2024). "However, due to rapidly emerging resistance to monotherapy based on BRAF inhibitors and the reactivation of the MAPK signaling pathway, the current standard treatment for melanoma is the use of a combined therapy based on, i.e., both MEK and BRAF inhibitors." (PMID 39175042, 2024). "Conversely, the oncogenic mutations, such as BRAF and NRAS, frequently found in other melanomas are generally absent in DMs." (PMID 38247727, 2024). "Cell-cycle analysis of melanoma cells grown in monoculture and co-culture shows no significant changes in BRAF inhibitor-mediated G1 arrest in the context of either CSF or standard medium, suggesting that the effects are independent of the cell cycle." (PMID 38866016, 2024). "This suggests that the synergistic rather than additive response to panRAF and MEK inhibition observed in NRAS mutant vs. BRAF mutant melanoma is driven by the sensitivity to negative feedback of the former compared to the latter." (PMID 39199684, 2024). "Furthermore, although this mutation had been reported in one NSCLC patient, one papillary thyroid carcinoma patient, and one melanoma patient, no data existed on whether this mutation contributed to BRAF activation or showed response to dabrafenib plus trametinib." (PMID 38766698, 2024). "However, despite the lower frequencies, BRAF, NRAS, KRAS, and KIT are somatic SNVs identified in canine melanomas, accounting for 1.8% (5/272), 8.0% (25/311), 13.1% (27/206), and 22.9% (16/70), respectively." (PMID 38397192, 2024). "Importantly, nivolumab improved RFS both in BRAF-WT (91.2% vs. 77.1%) and BRAFV600-mutant melanomas (87.3% vs. 81.7%)." (PMID 39727691, 2024). "Targeted therapies involving BRAF/MEK inhibitors and immunotherapy based on anti-PD1/anti-CTLA4 antibodies have achieved long-term survival rates of approximately 50% for patients with advanced melanoma." (PMID 38336727, 2024). "The BRAF-negative status of melanoma in our patient further accentuates the evolving landscape of therapeutic options, with immunotherapy emerging as a pivotal modality." (PMID 39119371, 2024). "A study using IMS detected greater proteomic changes in BRAF- and NRAS-mutated melanomas compared with melanomas without the mutations." (PMID 38247727, 2024). "In addition to the role of BRAF, the role of c‐MYC in the regulation of senescence in melanoma is also important." (PMID 39161800, 2024). "In the MAPK pathway, targeted therapies, such as BRAF-inhibitors (e.g., vemurafenib, dabrafenib) and MEK-inhibitors (e.g., trametinib), have been developed to specifically inhibit components of the MAPK pathway in melanomas." (PMID 38247727, 2024). "Of note, our previous in vitro and ex vivo work targeting PANX1 in melanoma employed murine B16‐F0, B16‐F1, B16‐F10, and human BRAF(V600E)‐mutant melanoma cell lines (A375‐P and A375‐M2) that do not entirely share the same genomic alterations of the BPC model." (PMID 38327091, 2024). "Since 2011, the treatment landscape for advanced melanoma has evolved rapidly, with the introduction of the first immune checkpoint inhibitor (ICI) and v‐raf murine sarcoma viral oncogene homolog B1 (BRAF) inhibitor in 2011, and mitogen‐activated protein kinase kinase (MEK) inhibitor in 2013." (PMID 39194340, 2024). "The performance of necroptosis or cuproptosis in BRAF inhibitor-resistant melanoma cells is not well evidenced." (PMID 38336727, 2024).
melanoma (continued). "CDKN2A was also enriched for non-duplication events (39/81, 48%) in BRAF-mutant cutaneous melanomas compared with the other genomic subtypes." (PMID 38758740, 2024). "Unlike WT cases, BRAF-mutant melanomas are more prone to brain metastasis and are often localized in areas with limited sun damage." (PMID 38539548, 2024). "On the other hand, in wild-type melanoma, anti-BRAF+/−MEK therapies are not indicated, and ICIs are the treatments that have been demonstrated to improve overall survival." (PMID 39000050, 2024). "For instance, nonacral melanoma (NAM) is primarily attributable to UV radiation and is associated with increased BRAF mutations." (PMID 38469735, 2024). "In a zebrafish melanoma residual disease model, an ALDH1-high subpopulation emerges following BRAF inhibitor treatment, and targeting these with an ALDH1 suicide inhibitor, nifuroxazide, delays or prevents BRAF inhibitor drug-resistant relapse." (PMID 38963759, 2024). "Immune checkpoint inhibitor therapy targeting CTLA-4 or programmed cell death protein 1 (PD-1) and its ligand (PD-L1) and targeted therapy with kinase inhibitors (BRAF and mitogen-activated extracellular signal-regulated kinase (MEK) inhibitors) are the current standard treatments for melanoma." (PMID 38540310, 2024). "In BRAF-therapy-resistant melanoma, combinatorial treatment with CSF-1R (PLX3397) and BRAF V600E (PLX4720) inhibitors at a low dose strongly increased the survival rate of murine xenograft models, as well as decreased the proliferation and invasiveness of cancer cell lines." (PMID 38254773, 2024). "Still, in BRAF wt patients with high levels of LDH, combination therapy is not significantly superior to ICI alone, which also indicates some limitations of LDH as a biomarker for melanoma." (PMID 38835341, 2024). "Interestingly, BRAF-mutant metastatic melanomas have increased CD4+ T cells and B cells but reduced CD8+ T cell infiltration versus BRAF wild-type samples." (PMID 39582535, 2024). "Acral melanoma typically has a lower mutation burden and lower rates of B-RAF proto-oncogene (BRAF) and neuroblastoma RAS viral oncogene homolog (NRAS) mutations as compared to its non-acral melanoma counterparts." (PMID 39001457, 2024). "Although targeted drugs have been developed, the response rate may reach 80% in melanoma but just 5% in CRC, eliciting the urgent need for mechanistic research on the poor prognosis of BRAF V600E CRC patients." (PMID 37973552, 2024). "In one study, mice having BRAF V600E-mutant melanoma with or without deletion of phosphatase and tensin homolog (PTEN) and active beta-catenin were involved in molecular profiling." (PMID 39336897, 2024). "It is notable that the four genomic subtypes of melanoma (BRAF, NRAS, NF1, and triple wild type) do not have distinguishing histopathological features or sites of origin (cutaneous, acral, mucosal, and uveal)." (PMID 38539487, 2024). "Moreover, activation of BRAF and RAS as well as NF1 can subsequently activate the MAPK signaling pathway, the most important pathway mediating melanoma metastasis." (PMID 37277447, 2023). "Alicea Gmet al. observed that aging fibroblasts increase the production of neutral fatty acids in the body, which are absorbed and converted into energy by melanoma cells through the fatty acid transporter (FATP2), protecting cancer cells themselves from BRAF-targeting drugs." (PMID 37174106, 2023).
melanoma (continued). "The large-scale analysis presented here indicates that the correlation of MALAT1 and MAPK kinase gene expression increases in melanoma and the relative expression of MALAT1 to the MAPK-pathway genes NRAS, BRAF, MEK1, MEK2, ERK1 and ERK2 is strongly reduced in melanoma, when compared to healthy skin." (PMID 37235843, 2023). "There has been a suspicion that the natural history of BRAF and NRAS mutant melanoma is more aggressive than melanomas lacking these mutations." (PMID 37444637, 2023). "The phosphorylation of phosphatidylethanolamine binding protein 1 (PEBP1)—a suppressor of the BRAF/MEK/ERK pathway—via RIPK4 observed in pancreatic cancer did not occur in melanoma." (PMID 36765875, 2023). "MALAT1 and BRAF expression was significantly correlated in both non-cancerous skin (p < 0.001) and in melanoma (p < 0.001), with the correlation being even stronger in melanoma." (PMID 37235843, 2023). "In contrast to parental cells, chronic-treated BRAF-inhibitor resistant melanoma cell lines did not decrease phospho-ERK1/2 or phospho-S6 levels when subjected to BRAF inhibitor." (PMID 37277330, 2023). "The same germline MITF PV was found in another patient (#62) with BRAF V600+ melanoma non-responding to both first-line and second-line therapies with TT and ICI agents, respectively." (PMID 36901733, 2023). "Similarly, the combination of a BRAF inhibitor and a MEK inhibitor triggers pyroptosis, leading to increased DC activation and T-cell infiltration in melanoma cells." (PMID 37373523, 2023). "Furthermore, the BRAF/MEK combination has shown further improvement in clinical outcomes in advanced and in adjuvant melanoma patients." (PMID 36967525, 2023). "Similarly, depletion of both BRAF and CRAF has shown promising effects on NRASQ61L/K mutant melanoma cells." (PMID 38111008, 2023). "Thus, the combination of BRAF inhibitors with inhibitors against EZH2 or against downstream targets of EZH2, such as PLK1, represent new therapeutic options for melanoma." (PMID 36768289, 2023). "Using a large panel of patient-derived tissue samples, we further show that MALAT1 expression correlates significantly with RNA expression of genes coding for the MAPK-pathway key kinases NRAS, BRAF, MEK1/2 and ERK1/2 in healthy skin, and notably to a greater extent in melanoma." (PMID 37235843, 2023). "For high-risk individuals (stages II B, C, D, and stage III), the mutational analysis of primary tumor or metastases is performed in order to offer adjuvant treatment, i.e., targeted treatment (mainly BRAF and MEK inhibitors for BRAF mutant melanoma) or immune checkpoint inhibitors (ICI)." (PMID 37387784, 2023). "Navitoclax in combination with dabrafenib and trametinib is still a subject of active study, not recruiting phase I/II clinical trial in patients with BRAF-mutant melanomas (NCT01989585)." (PMID 37835493, 2023). "Vemurafenib has been used since 2011 as an inhibitor of v-raf murine sarcoma viral oncogene homolog B1 (BRAF) kinase activity; however, diverse mechanisms of resistance have been identified in melanoma, which often leads to disease progression in patients carrying this mutation." (PMID 37445794, 2023). "To gain further insight into the potential interactions between MALAT1 and MAPK pathway signaling regulators, we analyzed the expression patterns of MALAT1 with NRAS, BRAF, MEK1, MEK2, ERK1 and ERK2 in a large dataset of healthy skin and melanoma patient samples." (PMID 37235843, 2023). "BRAF and CRAF are both required to drive ERK activation in mutant NRAS-dependent melanomas; however, the role of the various RAF proteins during resistance is unknown." (PMID 36765910, 2023). "As such, the success of this combination, similar to the combination targeting BRAF and MEK in melanoma and colorectal cancer, may be attributed to the synergistic effects on the same cellular pathway leading to more significant." (PMID 36978140, 2023).